IFIT1 (interferon induced protein with tetratricopeptide repeats 1)
Diseases named in the same sentence as IFIT1 in open-access papers (continued):
Sharing a sentence is not in itself a finding about the gene and the disease.
pneumonia (2 papers, 2017 to 2021). An acute, acute and chronic, or chronic inflammation focally or diffusely affecting the lung parenchyma, caused by an infection in one or both of the lungs (by bacteria, viruses, fungi, or mycoplasma.). "In an independent set of samples assayed using RT-qPCR, Ifnar2 and the interferon-responsive genes Cxcl11, Ifit1, Irf5 and Isg15 were confirmed to be upregulated during pneumonia." (PMID 28900269, 2017). "Interestingly, in the interferon signaling pathways, Ifnar2 and the interferon-responsive genes Cxcl11, Ifit1, Irf5 and Isg15 were verified to be upregulated during pneumonia, documenting that neutrophils are well able to respond to type I interferon signaling." (PMID 28900269, 2017).
prostate carcinoma (2 papers, 2022 to 2024). A carcinoma that arises from epithelial cells of the prostate gland. "We further confirmed the dose-dependent induction of IFIT1 expression by NDNB1182 in human prostate cancer cell line DU145." (PMID 36341371, 2022). "One notable exception was prostate cancer in which neither of the PGCC signatures but rather the 5-gene core signature of late progeny (FN1, INPP5D, ITGB4, ARHGDIB, IFIT1) was significantly predictive of outcomes." (PMID 38447798, 2024).
Skin cutaneous melanoma (2 papers, 2023 to 2024). "IFIT1 expression was supported as a prognostic biomarker in five independent TCGA cohorts including KIRC, KIRP, Skin cutaneous melanoma (SKCM), STAD, and UCEC." (PMID 38898490, 2024).
adenovirus infection (1 paper, 2023). "Of these, SOCS3, OASL, ISG15, and IFIT1 were found to be involved in the process of adenovirus infection and were thus regarded as candidate genes." (PMID 37017816, 2023). "Transcriptome sequencing showed that the expression levels of SOCS3, OASL, ISG15, and IFIT1 increased significantly over time, especially at 48 hpi (except SOCS3) and 72 hpi, suggesting that these genes might play an important role in adenovirus infection." (PMID 37017816, 2023).
AIDS (1 paper, 2015). A syndrome resulting from the acquired deficiency of cellular immunity caused by the human immunodeficiency virus (HIV). "Epidemiological studies indicate that lcSSc and anti-centromere-positive patients are often associated with other AIDs, including secondary Sjögren thyroiditis and PBC, where IFIT1 is known to play a critical role." (PMID 25880423, 2015).
allergic asthma (1 paper, 2022). A asthma with a basis in a pathological type I hypersensitivity reaction. "MX1, RSAD2, IFIT1, IFI27, OAS3, and SAMD9L were markedly elevated in HDM-treated mice and positively associated with IL-5, IL-13 and MUC5AC (key mediators of allergic asthma)." (PMID 36211429, 2022). "Furthermore, MX1, RSAD2, IFIT1, IFI27, OAS3, and SAMD9L levels correlated positively with IL-5, IL-13, and MUC5AC levels, which are the key mediators of allergic asthma." (PMID 36211429, 2022).
Aortic Rupture (1 paper, 2022). The tearing or bursting of the wall along any portion of the AORTA, such as thoracic or abdominal. "OAS3, IFIT1, and IFI44L may be predictive factors for aortic rupture." (PMID 36158807, 2022).
breast tumors (1 paper, 2014). "Low or defective TAP1 in breast tumors predicts higher risks for developing metastasis and down-regulation of the interferon-stimulated genes IFIT1 and MX1 has been linked to immune evasion mechanisms and tumor progression." (PMID 24870930, 2014).
colon cancer (1 paper, 2017). "Importantly, this is the first report showing that IFIT1 and IFIT2 are negatively regulated by Wnt signaling in colon cancer." (PMID 29245969, 2017).
colorectal adenoma (1 paper, 2017). An adenoma that arises from the colon or rectum. "In addition, two datasets (GSE4183 and GSE8671) revealed that expression levels of IFIT1 and IFIT2 were also down-regulated in colorectal adenoma tissues compared with normal tissues." (PMID 29245969, 2017).
diabetes (1 paper, 2024). "As Mx1, Ifit1, and Oas1 ISGs were increased in young mice, it seems probable that the increase in these ISGs contributed to diabetes onset." (PMID 38487540, 2024).
Granuloma (1 paper, 2014). A compact, organized collection of mature mononuclear phagocytes, which may be but is not necessarily accompanied by accessory features such as necrosis. "The stimulation of type 1 IFN pathway (OAS2 and IFIT1 genes) was similar in granulomas from healthy controls or patients with Q fever." (PMID 25566510, 2014). "We investigated the expression of IFIT1 and OAS2, two genes belonging to type 1 IFN pathway which were specifically modulated in C. burnetii-induced granulomas." (PMID 25566510, 2014). "The expression of IFIT1 genes and OAS2 genes was similar in C. burnetii-induced granulomas from patients with Q fever and healthy controls." (PMID 25566510, 2014).
head and neck cancer (1 paper, 2024). A primary or metastatic malignant neoplasm affecting the head and neck. "IFIT1 and IFITM3 are highly expressed and associated with poor prognosis in head and neck cancer." (PMID 39329063, 2024).
heart failure (1 paper, 2023). Inability of the heart to pump blood at an adequate rate to meet tissue metabolic requirements. "The increase in ifit-1 in the MDO group indicates the progression of apoptosis associated with OS, which has an impact on cardiomyocyte viability and could result in heart failure." (PMID 37047815, 2023).
ischemic cardiomyopathy (1 paper, 2021). Ischemic cardiomyopathy is a cardiomyopathy in which a weakness in the muscle of the heart due to inadequate oxygen delivery to the myocardium with coronary artery disease being the most common cause. "IFIT3 may be a potential therapeutic target for ischemic cardiomyopathy, and IFIT1 and IFIT5 are key genes that are used to predict treatment response in patients with microvascular disease in the early stage." (PMID 34753383, 2021).
lymph node metastasis (1 paper, 2024). "In addition, IFIT1 and IFIT3 have been reported to promote the lymph node metastasis of HNSC." (PMID 39392128, 2024).
neuroblastoma (1 paper, 2017). Neuroblastoma (NB) is the most common solid, extracranial childhood tumor. "In neuroblastoma cells, the poly(I:C) triggered inductions were significantly blunted by PINK1 knockdown for RSAD2, DDX58, IFIT3, and IFIT1." (PMID 28768533, 2017).
oral cancer (1 paper, 2018). "To determine whether the TAR RNA was able to directly induce expression of the same genes, we transfected TAR RNA into HSC3 and SCC9 oral cancer cells and found that TAR RNA significantly increased IFIT1, IFNB1, and DEFB103 expression in the cancer cells." (PMID 30389917, 2018).
papilloma (1 paper, 2012). A benign epithelial neoplasm that projects above the surrounding epithelial surface and consists of villous or arborescent outgrowths of fibrovascular stroma. "Human or mouse Ifit1 reportedly have antiviral activity in cell culture against human papilloma, Sindbis, Rift valley fever, and hepatitis C viruses, and in vivo against vesicular stomatitis virus." (PMID 22589727, 2012). "In cell culture, human and mouse IFIT1/Ifit1 reportedly have antiviral activity against several viruses including human papilloma, Sindbis, vesicular stomatitis, and hepatitis C viruses." (PMID 22589727, 2012).
psoriasis (1 paper, 2024). An autoimmune condition characterized by red, well-delineated plaques with silvery scales that are usually on the extensor surfaces and scalp. "On the contrary, in psoriasis, more inflammation-related spatially variable genes (e.g. SERPINF1, FKBP5, IFIT1/3, DDX58) were identified." (PMID 38433843, 2024).
rectal cancer (1 paper, 2025). A primary or metastatic malignant neoplasm that affects the rectum. "Given that multifractionated ionizing radiation induces the expression of immune response genes in vitro, we additionally explored whether the PARPs are co-expressed with selected OAS2, IFITM1, and IFIT1 genes in rectal cancer patients." (PMID 40646573, 2025).
Stroke (1 paper, 2011). Sudden impairment of blood flow to a part of the brain due to occlusion or rupture of an artery to the brain. "TGFβ, RANTES, and IFIT1 were significantly upregulated in the LPS-preconditioned brain compared to saline 24 hr following stroke." (PMID 21999375, 2011).
thyroid cancer (1 paper, 2023). "To dig the effect of IFIT1 on thyroid carcinoma cells, we knockdown IFIT1 using siRNAs targeting to IFIT1." (PMID 37817224, 2023). "The mRNA and protein level of IFIT1 was regulated by KLF13 expression in thyroid carcinoma." (PMID 37817224, 2023). "In conclusion, KLF13 may function as an anti-tumor protein in THCA by regulating the expression of IFIT1 and offer a theoretical foundation for treating thyroid carcinoma." (PMID 37817224, 2023). "Thus, our work demonstrates that the tumor suppressor effect of KLF13 on thyroid carcinoma, which is mediated by regulation of IFIT1 expression through binding to its promoter region." (PMID 37817224, 2023). "The relative mRNA level of IFIT1 was significantly increased in siKLF13#1 transfected K1 and TPC1 cells, while greatly decreased in KLF13 overexpressed thyroid cancer cells." (PMID 37817224, 2023).
triple-negative breast carcinoma (1 paper, 2025). An invasive breast carcinoma which is negative for expression of estrogen receptor (ER), progesterone receptor (PR), and human epidermal growth factor receptor 2 (HER2). "Moreover, in a subset of patients with triple-negative breast cancer (TNBC), IFIT1 positivity was found to correlate with improved LRFS and DFS at 10 years, suggesting that IFIT1 may serve as a biomarker for treatment stratification." (PMID 40564154, 2025).
infection (325 papers, 2007 to 2026). The state of being infected such as from the introduction of a foreign agent such as serum, vaccine, antigenic substance or organism. "To evaluate the diagnostic accuracy of two hub genes, RSAD2 and IFIT1, in predicting infection status, we performed ROC analysis on HPV16-infected and GV-infected samples across different datasets." (PMID 40510586, 2025). "Peptides TAT-I24 and TAT-M26, which were able to cause significant inhibition of ie1 gene expression, also caused a significant reduction of Ifit1, Ccl7 and Ccl5 expression 2 h post-infection." (PMID 35806257, 2022). "Most interestingly, in contrast to Huh7, even a very low-level induction of p21 was sufficient to significantly reduce SARS-CoV-2 susceptibility and among the ISGs IFIT1 showed an observable increase upon infection." (PMID 34006825, 2021). "In comparison, a deficiency of Ifit1 was associated with increased infection by WNV-E218A, which likely secondarily resulted in enhanced recruitment of lymphocytes to the CNS." (PMID 22589727, 2012). "Ex vivo infection experiments revealed cell-type specific differences in the ability of Ifit1 deficiency to rescue the replication defect of WNV-E218A." (PMID 22589727, 2012). "Because a deficiency of Ifit1 did not alter pathogenesis of wild type WNV, we conclude that the viral 2′-O methyltransferase encoded by NS5 largely overcomes Ifit1-mediated control of infection." (PMID 22589727, 2012). "Ex vivo infection experiments revealed cell-type specific differences in the ability of an Ifit1 deficiency to complement the replication defect of WNV-E218A." (PMID 22589727, 2012). "Our ex vivo infection experiments revealed cell-type specific differences in the ability of a deficiency of Ifit1 to rescue the replication defect of WNV-E218A." (PMID 22589727, 2012). "IFN-induced proteins with tetratricopeptide repeats (IFITs) could be generated through the IFN-γ–JAK–STAT1/2 pathway to fight against pathogen infection, and IFIT1-deficiency mice are more sensitive to Burkholderia cenocepacia." (PMID 33392192, 2020). "As such, we noticed a more pronounced difference between wild-type and Ifit1-deficient cells following a low multiplicity infection, since type I IFN from infected cells will induce naïve cells to establish an antiviral state, including the upregulation of Ifit1 expression." (PMID 31372503, 2019). "In contrast, the loss of IFIT1 in many rodents might leave them more susceptible to infection by viruses inhibited by IFIT1, such as VSV." (PMID 27240734, 2016). "Indeed, the computed top DEG, typifying each cluster on day 3 in the effector phase of infection, hosted several interferon-induced anti-viral genes (Irf1, Irf7, Ifrd1, Socs1, Socs3, Ifit1, Bst2, and Isg15) as well as genes associated with mature resident Trm cells (Cd69, Nfkbid, Brd2, FosB)." (PMID 35260804, 2022). "This increased IFN signature during nsp15mut infection was also observed at the protein level in both cell types using western blots for IFIT1 and Viperin protein expression." (PMID 41369222, 2026). "Similar to our findings made by EPO of HepG2/C3A cells, expression of ISG15, IFNL1, and an additional ISG, IFIT1, peaked on day 5 post-ΔORF2 infection and decreased again to a similar level as WT on day 7 post-infection." (PMID 40982567, 2025). "Differential gene expression analysis in hROs at 24 h post-infection revealed a robust upregulation of antiviral genes (e.g. IFIT1, IFIT2, MX1, and OAS2) and pathways related to antiviral innate immunity and viral replication in rRVFV versus mock comparisons." (PMID 41255708, 2025). "Isg15 and Ifit1/Isg56 (interferon-induced protein with tetratricopeptide repeats 1) mRNA expression were detected 12 h post infection with levels of Isg15 and Ifit1/Isg56 mRNA 5-fold greater in ΔWD MEFs compared to WT controls." (PMID 40143422, 2025).
infection (continued). "In particular, we demonstrated a significant upregulation of the IFIT1/2-CXCL10 axis upon infection of the highly differentiated pseudostratified primary human respiratory epithelium with SARS-CoV-2 Delta on day 3 post infection." (PMID 40510596, 2025). "In human macrophages, HIV-1 induces a sustained increase in IFIT1 expression from 3 to 9 days post infection." (PMID 41041557, 2025). "Following the methodology described in Section 2.3, we identified three genes: IFIT1 (infection-dependent), IFIT2 (infection-dependent), and ELOVL4 (time-dependent), using GLMQL-RMAS as predictors for multinomial logistic regression." (PMID 38655085, 2024). "Despite this, we observed a significant increase in the fold induction of both RIG-I and IFIT1 following infection by wt SeV compared to Pmut SeV." (PMID 39494910, 2024). "Infection with MR766MC chimera expressing NS1CWA protein resulted in a lower magnitude of IFIT1 and Viperin mRNA induction in A549 cells compared to parental virus." (PMID 39178324, 2024). "Ifit1 and Ifit2 are induced in response to dsRNA, type I and type II IFNs, and infection by various viruses." (PMID 39077737, 2024). "While examining the persistent effects of ts SeV infection in cells after shifting to 37°C, we assessed the transcriptional upregulation of two interferon-stimulated genes (ISGs): RIG-I and IFIT1 following infection of 293T cells." (PMID 39494910, 2024). "Neutrophils, which were identified in the brain at only small relative abundance, dramatically expanded in the blood after infection and upregulated antiviral response genes, including Ddx58, Ifih1, Ifit1, Ifit2 and Isg15." (PMID 39749347, 2024). "qPCR results indicated that PTK2B overexpression significantly enhanced the mRNA levels of Ifnb1, Ifit1 and Cxcl10 induced by infection with HSV1-GFP or VSVΔM51-GFP in MEFs." (PMID 37989995, 2023). "To more precisely assess when innate immune activation occurs throughout infection, we determined the onset of IFIT1 transcription and found that over 90% of the IFIT1+ cells activate IFIT1 transcription between 5 and 10 h after initial replication." (PMID 37814072, 2023). "IFIT1 restricts the infection of both RNA and DNA viruses, including RSV, HCV, VSV, Japanese encephalitis virus (JEV), hepatitis B virus (HBV), and others." (PMID 37515100, 2023). "Together, these experiments establish IFIT1 expression as a sensitive marker for cells that sense intracellular infection through viral dsRNA and activate an antiviral response." (PMID 37814072, 2023). "Shared genes upregulated with a higher log2 fold change in B/Victoria infection included known anti-viral proteins IFIT1-3, IFITM1, MX2, IFI44L and ISG15 along with mitochondrial-related gene CMPK2." (PMID 37766362, 2023). "Second, we knocked down Ptk2b in mouse macrophages RAW 264.7 cells and found that Ptk2b knockdown significantly impaired mRNA levels of Ifnb1, Ifit1 and Cxcl10 induced by infection with HSV1-GFP." (PMID 37989995, 2023). "Ifit1, a marker for immune response to LPS infection in macrophages, is upregulated in LPS-stimulated cells but not in T. gondii infected cells." (PMID 37575232, 2023). "qPCR results showed that Ptk2b deficiency dramatically reduced mRNA levels of Ifnb1, Ifit1 and Cxcl10 stimulated by HSV1-GFP or VSVΔM51-GFP infection." (PMID 37989995, 2023). "Infection with sh-circ_0086296 inhibited circ_0086296 expression, increased miR-576-3p expression, and decreased IFIT1 levels in aorta tissues of atherosclerotic mice." (PMID 36138395, 2022). "The IFIT1 gene was upregulated by ~350 fold upon P/V/F mutant infection, with a much lower induction by the WT infection." (PMID 35631014, 2022). "In A549-ACE2 cells, we also observed a slight increase in IFNβ transcript levels at 24 h and IFIT1 transcript levels at 48 h post infection." (PMID 35022513, 2022). "IFIT1 and Mx were up-regulated by the wt virus and down-regulated following infection with the mutant strain." (PMID 35215144, 2022).